MMP9 (matrix metallopeptidase 9)
Diseases named in the same sentence as MMP9 in open-access papers (continued):
Sharing a sentence is not in itself a finding about the gene and the disease.
breast carcinoma (continued). "Taken together, our findings indicate that the MMP-9 inhibitory activity of glaucine and its abilities to attenuate IκBα and NF-κB activities may be therapeutically useful as a novel means of controlling breast cancer growth and invasiveness." (PMID 25670016, 2015). "Thus, repression of CD44 and MMP9 by the inhibition of NF-κB could be responsible for the decreased invasiveness seen in breast cancer cells." (PMID 25184276, 2014). "Therefore, the aim of the present study was to determine whether the combined detection of VEGF and MMP-9 is valuable for the diagnosis, treatment and prognosis of breast cancer." (PMID 24944618, 2014). "Fascin and MMP-9 might be markers of aggressive behaviour in breast cancer." (PMID 24993803, 2014). "Thus, MMP-9 is a potential clinical marker for breast cancer progression and metastasis." (PMID 24845596, 2014). "Moreover, overexpression of MMP-9 might play a critical role in degradation of extracellular matrix to enhance the invasive and metastatic capacity of breast cancer." (PMID 24993803, 2014). "Furthermore, the CXCR4/PI3K/AKT/MMP-9 pathway may be important in the bone metastasis of breast cancer." (PMID 24959222, 2014). "Consequently, we hypothesize that the CXCR4/PI3K/AKT/MMP-9 signaling pathway is involved in the bone metastasis of breast cancer." (PMID 24959222, 2014). "Thus, as a proteolytic enzyme, MMP-9 may affect the early progression of lymphangiogenesis and lymphatic metastasis of breast cancer." (PMID 24845596, 2014). "Thus, MMP-9 is a potential marker for breast cancer progression." (PMID 24845596, 2014). "Hence, MMP-9 is a promising prognostic biomarker of high-grade breast cancer." (PMID 25151367, 2014). "Therefore, inhibiting MMP-9 expression and/or its upstream regulatory pathways might be critical in treating malignant tumors, including breast carcinoma." (PMID 24885456, 2014). "An increased expression of MMPs, particularly MMP-2 (gelatinase A; 72-kDa type IV collagenase) and MMP-9 (gelatinase B; 92-kDa type IV collagenase), has been correlated extensively with the malignancy of tumors and poor survival among patients, especially those with breast cancer." (PMID 23878598, 2013). "We evaluated genetic variation in MMP1 (9 SNPs), MMP2 (8 SNPs), MMP3 (4 SNPs), and MMP9 (3 SNPs) and breast cancer risk among Hispanic (2111 cases, 2597 controls) and non-Hispanic white (NHW) (1481 cases, 1586 controls) women in the Breast Cancer Health Disparities Study." (PMID 23696797, 2013). "In addition, targeting NF-κB signaling may also inhibit breast cancer cell invasion through decreasing matrix metalloproteinase 9 (MMP-9) expression." (PMID 23618129, 2013). "Therefore, we hypothesize that RABEX-5 promotes the migration and invasion of breast cancer cells through activation of MMP-9." (PMID 23941575, 2013). "Thus, our data suggest that MMP-2 and MMP-9 may play fundamental roles in breast cancer invasion and metastasis." (PMID 23935727, 2013). "Therefore, we analyzed the expression of candidate proteases in c-myb-overexpressing and control MDA-MB-231 cells and confirmed the differential expression of MMP1, MMP9, and cathepsin D. We confirmed the recent observation by Bhattarai that the c-Myb upregulates MMP9 in breast cancer cells." (PMID 22439866, 2012). "Not only the key roles of MMP-9 in tumorigenesis but also their characteristics of being secreted into the blood stream have inspired many researchers to evaluate the associations between circulating level of MMP-9 and clinicopathological characteristics of breast cancers." (PMID 22640376, 2012). "Immunohistochemical and statistical analysis found that MMP-2 and MMP-9 expressions are positively related to HER2 overexpression in the stromal cells of breast carcinoma, implicating that MMP-2 or MMP-9 may be a responsive gene of HER2 signaling in breast cancer metastasis." (PMID 19617202, 2011).
breast carcinoma (continued). "Thus, we postulated that the action mechanism of pterostilbene against cell invasion and metastasis of breast carcinoma might include the regulation or interference with these signaling pathways responsible for HRG-β1-mediated MMP-9 induction." (PMID 19617202, 2011). "To investigate whether cholesterol could regulate uPAR and MMP-9 in breast carcinoma, we used MβCD (methyl beta cyclodextrin, which extracts cholesterol from lipid rafts) to disrupt lipid rafts and studied its effect on breast cancer cell migration, invasion, angiogenesis and signaling." (PMID 21106094, 2010). "Therefore, decreasing cholesterol levels by LR disruption could provide a good strategy to prevent MMP-9 and uPAR-mediated degradation of the extracellular matrix in breast carcinoma." (PMID 21106094, 2010). "The study examined the regulation of PD-1, PD-L1, MMP-9, AGEs, AOPPs, IL-6, 8-OHdG and TNF-α expression in a rat model of breast cancer induced by DMBA." (PMID 40008130, 2025). "The inhibitory potential of rosmarinic acid on MMP-1, MMP-2, MMP-9, and MMP-12 will limiting their ability to promote proliferation, invasiveness, angiogenesis, and metastasis of breast cancer cells." (PMID 40176865, 2025). "SB5 suppressed both MMP9 and spheroid formation in prostate cancer (RV1) cell line and breast cancer (MCF‐7) cell line differently than SB4 but both compounds did not affect the VDAC1 protein expression." (PMID 41179704, 2025). "Silibinin downregulates the expression of the key migration regulators MMP-2 and MMP-9 through the Jak2/STAT3 and MEK/ERK pathways in breast cancer." (PMID 41470858, 2025). "Among those 11 protein candidates, we found 6 proteins that are involved in the progression and development of breast cancer, those are MMP-1, MMP-2, MMP-9, MMP-12, M-phase inducer phosphatase-2 (CDC25B), and Aldose reductase." (PMID 40176865, 2025). "MMP‐9 related to integrin β6 degrades FN, leading to FAK–Src interaction and promoting breast cancer cell invasion and migration through the Erk1/2 and PI3K/Akt/Smad‐1/5/8 pathways." (PMID 41377763, 2025). "It was previously shown that MMP-2 and MMP-9 activity is increased by TGFβ1 treatment in a time- and dose-dependent manner in HCC1806 breast cancer cells." (PMID 40535569, 2025). "In MCF-7 breast cancer cells, orientin inhibited migration and invasion by suppressing the PKCα/ERK/AP-1/STAT3 signaling axis, leading to decreased expression of matrix metalloproteinase-9 (MMP-9) and interleukin-8 (IL-8)." (PMID 40725115, 2025). "Gelatinase-B or MMP9 can upregulate several genes as regulator of the malignant phenotype, also affecting the breast cancer phenotype." (PMID 40176865, 2025). "Accordingly, our complex network model of HER2-overexpressing breast cancer suggests the therapeutic potential of inhibiting MMP2 and MMP9 as a strategy to target tumours." (PMID 40259907, 2025). "Gene expression correlation analysis revealed that USP30 negatively correlates with the expression of stem cell markers such as MMP2, MMP9, MYC, OCT4(POU5F1), NANOG, ALDH1A3, CD133 (PROM1), EPCAM, CD24, and ITGA6 in breast cancer cohorts." (PMID 41306556, 2025). "In a humanized breast cancer mouse model, LSD1 inhibition resulted in reduced FLI1 target gene signatures related to angiogenesis (VEGFA, FGF-1, MMP-1, MMP-9), migration, and invasion (PLAU)." (PMID 41300765, 2025). "Similar findings have been seen in breast cancer, with DHA decreasing metalloproteases such as MMP2 and MMP9 as well as vimentin and reducing cell migration." (PMID 41009329, 2025). "Research findings suggest that FN contribute to the metastasis and invasion of breast cancer by amplifying MMP-2 and MMP-9 levels." (PMID 40940401, 2025). "The overexpression and secretion of MMP9 enhance the permeability of the BBB, thereby facilitating the transendothelial migration of breast cancer cells and promoting the BCBM." (PMID 41219968, 2025).
breast carcinoma (continued). "In the present study, the poor prognosis of MDA-MB-231 and MCF-7 breast cancer cell lines is indicated by the inhibition of MMP2 and MMP9 by RT and/or abemaciclib." (PMID 40035822, 2025). "NOB can downregulate CXCR4 and MMP-9 as well as the activity of MMP-9 by inhibiting NF-κB and activating MAPKs, thereby reducing the invasion of breast cancer cells." (PMID 41425709, 2025). "The M2 macrophages subsequently secrete immunosuppressive molecules (e.g., arginase 1 [Arg1], CD206) and metastasis-promoting factors such as matrix metalloproteinase 9 (MMP9), collectively accelerating breast cancer lung metastasis." (PMID 40564894, 2025). "Using this methodology, we identified nine proteins—FN1, VWF, PRG4, MMP9, CLU, PRDX6, PPBP (CXCL7), APOC1, and CHL1—that were robustly quantified in serum and showed statistically significant differences between breast cancer patients and healthy controls." (PMID 40940928, 2025). "Following MMP‐9 degradation of fibronectin, the interaction between FAK and Src promotes the invasion of breast cancer cells." (PMID 41377763, 2025). "The S100A1+subpopulation promotes a pro-inflammatory microenvironment and accelerates angiogenesis and matrix remodeling by releasing leukotriene B4(LTB4), ROS, and matrix metalloproteinase-9(MMP9), directly facilitating breast cancer metastasis." (PMID 40568594, 2025). "In breast cancer cell lines, elevated PrPc expression led to increased expression of MMP9 at both mRNA and protein levels through the activation of NF-κB and ERK pathways, contributing to the heightened motility of breast cancer cells." (PMID 39972491, 2025). "NE and MMP9 in NETs promote ECM remodeling, activating the integrin α3β1-FAK/ERK/MLCK/YAP signaling pathway to enhance dormant tumor cell proliferation in breast cancer." (PMID 40564191, 2025). "Mammary tumors that are invasive and have a poor prognosis are related to overexpression of MMP2 or MMP9." (PMID 40735254, 2025). "Overall, both MMP9 and MMP2 have been identified as promising markers for predicting the prognosis of patients with breast cancer." (PMID 39057065, 2024). "Here, we report that DOX therapy induced increased circulating levels of the neutrophil markers PGLYRP1, CAMP, MMP9, and CEACAM8 early after a single dose of chemotherapy in breast cancer patients." (PMID 39273682, 2024). "In breast cancer MCF-7 cells exposed with 12-O-tetradecanoylphorbol-13-acetate (TPA), luteolin inhibited the production of IL-8 and the activation of MMP-9." (PMID 39834817, 2024). "In a study of 55 female breast cancer patients revealed a significant correlation between LCN2 and MM9 levels, suggesting its potential utility in predicting MMP9 levels." (PMID 39188682, 2024). "The increased expression of MMP9, orchestrated by BMAL1, enhances the invasive potential of breast cancer cells, contributing to their ability to invade and metastasize." (PMID 38361941, 2024). "Our in vitro findings are corroborated by co-expression of elevated MMP-9 with TGF-β and TNF-α in human breast cancer tissues." (PMID 39351229, 2024). "Related experiments in human breast cancer cells and nude mice also demonstrated that SFN inhibited breast cancer development by inhibiting NF-κB and suppressing MMP-9 expression." (PMID 38902597, 2024). "There is no study investigating a similar correlation in animal tumors; however, in human tumors such as breast cancer, a positive correlation between COX-2 and MMP-9 expression has been reported, which is the opposite to the results obtained in this study." (PMID 39061572, 2024). "This leads to a reduction in EGF expression, subsequent downregulation of matrix metallopeptidase 9 (MMP-9), and suppression of breast cancer metastasis." (PMID 39199245, 2024). "Individually, MMP-9, TNF-α, and TGF-β are integral contributors in the complicated and multifaceted process of breast cancer metastasis." (PMID 39351229, 2024).
breast carcinoma (continued). "In this study, we evaluated the potential of the neutrophil biomarkers PGLYRP1/TAG7, CAMP/LL37, MMP9, and CEACAM8/CD66b to predict DOX-induced cardiotoxicity in patients with early-stage breast cancer." (PMID 39273682, 2024). "siRNA-mediated knockdown of NSD2 in our breast cancer cell model significantly abolished the cooperativity between TGF-β and TNF-α for promoting MMP-9 expression, confirming the pivotal role of H3K36m2 chromatin active mark in this synergy." (PMID 39351229, 2024). "In breast cancer, crocin suppresses metastatic breast cancer progression via VEGF and MMP-9 down-regulations both in vitro with 4T1 cell line and in vivo with BALB/c mice." (PMID 39334719, 2024). "MMP-9, TNF-α, and TGF-β are integral contributors to the complicated and multifaceted process of breast cancer metastasis." (PMID 39351229, 2024). "In breast cancer, increased secretion and activation of MMP-2 and MMP-9 promote tumor cell invasion into other tissues and metastasis to distant organs." (PMID 38737746, 2024). "ORL inhibits angiogenesis (VEGF, MMP-9, and CXCR4/CXCL12) and fatty acid synthesis (ACLY, ACC, and FASN) genes and protein expression with the induction of apoptotic genes in different breast cancer cell lines." (PMID 38256929, 2024). "In TN breast cancer, NT stimulates invasion and migration through NTR1 activation, leading to matrix metalloproteinase-9 (MMP-9) expression, which is crucial for invasion." (PMID 39519199, 2024). "Using a well-established MDA-MB-231 breast cancer model, we found that the synergy between TGF-β and TNF-α led to MMP-9 upregulation at the transcriptional and translational levels, compared to treatments with each agent alone." (PMID 39351229, 2024). "In the present study, DiMeOC-Mg-BCD was found to inhibit the expression of MMP9 and MMP2 genes in the MDA-MB-231 breast cancer cell line." (PMID 38673967, 2024). "In summation, our findings elucidate a novel interplay in breast cancer cells, where GATA4 curtails the influence of the p65/p50 complex on MMP9 expression by interacting with p65." (PMID 38653973, 2024). "FOXO3a promoted invasive migration by inducing the expression of matrix metalloproteinase 9 (MMP-9) and MMP-13, whereas depletion of FOXO3a in breast cancer cells leads to decreased tumor size specifically due to attenuated invasive migration." (PMID 38714753, 2024). "Breast cancer tissue samples that stained intensely for TNF-α and TGF-β expression revealed markedly increased MMP-9 expression." (PMID 39351229, 2024). "Previously, it has been demonstrated that in MCF7 breast cancer cells, STAT3 collaborates with FRA1 and c-JUN AP1 components to activate the MMP9 promoter, while in HepG2 hepatoma cells, STAT3 associates with HDAC1 to inhibit IL6-induced CCL2 transcription." (PMID 39274912, 2024). "We demonstrate a novel function of IGFBP5 in the regulation of IGF-IR expression, migration and MMP-9 secretion induced by IGF-I and/or insulin, and in the spheroids formation in MCF-7 breast cancer cells." (PMID 38896333, 2024). "In this study we analyzed peripheral blood samples from 40 patients with early-stage breast cancer treated with DOX-based chemotherapy for protein and mRNA expression of PGLYRP1, CAMP, MMP9 and CEACAM8." (PMID 39273682, 2024). "In breast cancer, a relationship between the expression of the Twist factor with MMP-2 and MMP-9 was described and evaluated via immunohistochemistry." (PMID 38542313, 2024). "Using an MDA-MB-231 cell line model of breast cancer, we herein delve into the epigenetic mechanisms that drive the synergy between TGF-β and TNF-α, with implications for MMP-9 overexpression in the TME." (PMID 39351229, 2024). "The aim of this study was to validate previously determined mRNA biomarkers of DOX-induced presymptomatic cardiotoxicity, PGLYRP1, CAMP, MMP9, and CEACAM8 and to assay their protein expression in breast cancer patients’ circulation." (PMID 39273682, 2024).
breast carcinoma (continued). "IGFBP5 regulates IGF-IR expression, migration and MMP-9 secretion induced by IGF-I and/or insulin, and the spheroids formation in MCF-7 breast cancer cells." (PMID 38896333, 2024). "The results obtained at the ELISA measurements proved that the Les-6287 compound can decrease the concentration of MMP-2, MMP-9, and ICAM-1 proteins involved in metastasis and poor prognosis in breast cancer patients." (PMID 39199694, 2024). "Given the critical role of MMP9 in breast cancer metastasis and the inhibitory effect of GATA4 on MMP9 transcription, we sought to further assess the influence of GATA4 on breast cancer metastasis." (PMID 38653973, 2024). "We found that the MMP-9 and ICAM-1 concentrations in MCF-7 breast cancer cells were below the detection range." (PMID 39199694, 2024). "Owing to decreased expression of GSK-3, MMP-9, NF-B, and COX17, TUR revealed reduced lung metastasis of breast cancer." (PMID 38723038, 2024). "This study aimed to validate mRNA expression of the previously identified biomarkers of DOX-induced cardiotoxicity, PGLYRP1, CAMP, MMP9, and CEACAM8, and to assay their protein expression in the peripheral blood of breast cancer patients." (PMID 39273682, 2024). "Tumor-associated neutrophils by secreting the cytokine tissue inhibitor matrix metalloproteinase 1 (TIMP-1) induce breast cancer EMT and can also remodel the extracellular matrix via neutrophil collagenase (MMP8) and gelatinase B (MMP9)." (PMID 38715921, 2024). "It has been reported that during breast cancer invasion and metastasis, the secretion and activation of MMP-2 and MMP-9 increase." (PMID 38737746, 2024). "One study stated that breast cancer cell-secreted TNF-alpha and TGF-beta drive the expression of MMP-9 in stromal fibroblasts." (PMID 39351229, 2024). "miR-1258 expression leads to a decrease in HPSE levels and HPSE-related proteins: p-Akt, p-EGFR, MMP-9, COX2 consequently, leading to inhibition of brain metastasis by limiting breast cancer cell invasion." (PMID 39175471, 2024). "Lobie and group have shown an upregulation of MMP9 in endometrial cancer cells and an upregulation of MMP2 and MMP9 in breast cancer cells when treated with GH." (PMID 39123364, 2024). "ADAM8 enhances early metastatic events including transendothelial migration through upregulation of MMP-9 and liberation of PSGL-1 from breast cancer cells." (PMID 36910158, 2023). "In breast cancer cells, KLF8 also induces expression of MMP9, an enzyme critical for breaking through the extracellular matrix during cancer cell invasion and migration." (PMID 37152043, 2023). "MMP-9 is a secretory protein, and the current study observed the changes in MMP-9 expression in the whole cell lysate of breast cancer cells using Western blotting." (PMID 38068928, 2023). "To confirm the regulatory role of SRF in MMP gene expression in breast cancer cells, we used two different SRF-targeting siRNAs to knock down SRF and quantified the levels of MMP-9 and MMP-13 mRNAs using real-time RT-qPCR." (PMID 37266453, 2023). "THC treatment decreased the expression level of MMP-9 and MMP-2 in breast cancer cells and increased the expression level of TIMP2." (PMID 36707875, 2023). "Spleen macrophages carrying breast cancer tumors secrete higher levels of proinflammatory mediators CCL2, CXCL2, MMP-9, and CHI3L1 stimulating this increased secretion." (PMID 38003338, 2023). "For example, PNU-74654 can inhibit the migration and invasion of breast cancer (BC) cells by upregulating E-cadherin and downregulating MMP3 and MMP9 to synergistically enhance the anticancer effect of fluorouracil (5-FU)." (PMID 37763649, 2023).